ADAM10 (ADAM metallopeptidase domain 10)
Diseases named in the same sentence as ADAM10 in open-access papers (continued):
Sharing a sentence is not in itself a finding about the gene and the disease.
breast carcinoma (continued). "In breast cancer, circ_0000977 binds to miR-153 to counteract the inhibition of hypoxia-inducible factor 1-α (HIF1A) and a disintegrin and metalloproteinase domain-containing 10 (ADAM10)." (PMID 35464462, 2022). "Particularly, in breast cancer, differential secretion of exosomes displaying an array of proteins such as Tetraspanin CD9, HSP70, Annexin-1 and metalloprotease ADAM10 at various stages of breast cancer may contribute to an accurate diagnosis and prognosis." (PMID 34572899, 2021). "The aim of the present study is to investigate the potential roles of A Disintegrin and Metalloproteinase 10 (ADAM10) on TNBC cells and the effects of combining ADAM10 expression and neoadjuvant chemotherapy treatment (NACT) to improve the overall survival in breast cancer patients." (PMID 33413403, 2021). "To demonstrate whether ADAM10 affects TNBC functions by regulating the Notch1 signaling, we first detected the expression level of Notch1 in different breast cancer cell lines using the western blot and qRT-PCR assays." (PMID 33413403, 2021). "Similarly, several tetraspanins have been described to be enriched at the periphery of breast cancer cells and we have shown that expression of TSPAN5 in U2OS cells led to an enrichment of its partner ADAM10 at the cell periphery." (PMID 34445169, 2021). "Although ADAM10 was up-regulated in the triple-negative breast cancer cell line MDA-MB-231 37, the role of ADAM10 in the regulation of HR-positive breast cancer cells proliferation and migration is still unclear." (PMID 32328182, 2020). "ADAM-10 levels were significantly increased in subpopulations of CD9-positive exosomes isolated from the plasma and total blood fractions of patients with luminal breast cancer, as compared with HFs and triple-negative subtype BCPs." (PMID 32218180, 2020). "ADAM10 is also involved in the shedding of other receptors such as the HER2 receptor resulting in its constitutive activation and overexpression of ADAM10 has been reported in several malignancies including gastric, prostate, liver and breast cancer." (PMID 27187360, 2016). "Therefore, we studied the role of ADAM10 in relation to trastuzumab treatment and resistance in HER2 positive breast cancer." (PMID 24952873, 2014). "We hypothesized that ADAM10 expression might be relevant as a biomarker to predict prognosis and trastuzumab response in HER2 positive breast cancer patients." (PMID 24952873, 2014). "In our study, we specifically investigated whether ADAM10 and ADAM17 were responsible for constitutive shedding of GPNMB/OA in breast cancer cells, thus it is possible that ADAM17 is also capable of shedding GPNMB/OA in the context of PMA stimulation." (PMID 20711474, 2010). "In prostate and breast cancer cells, matrilysin (MMP-7) and stromelysin (MMP-3) have been shown to generate a soluble 80-kDa fragment, and ADAM-10, a transmembrane protease, controls constitutive and regulated shedding of E-cadherin in cell cultures of keratinocytes and in vivo in mouse embryos." (PMID 18478055, 2008). "Therefore, our results demonstrated that, in HER2+ breast cancer, trastuzumab treatment induced PM-to-ER retrograde transportation of DPAGT1, which protected ADAM10 from ERAD via N-glycosylation, consequently resulting in robust HER2 shedding, trastuzumab resistance, and poor clinical outcomes." (PMID 37463446, 2023). "Cholesterol depletion by methyl-beta-cyclodextrin in breast cancer cell lines increases vesicle release and treatment with pervanadate regulates ADAM10 relocation in microvesicles derived by the Golgi apparatus, while PMA favors ADAM10 transport to the cell membrane." (PMID 34067041, 2021). "miR-451 is downregulated in gastric cancer, breast cancer, and head and neck squamous cell carcinoma, where it executes tumor suppressor functions by targeting macrophage migration inhibitory factors and a disintegrin and metalloproteinase (ADAM) protein family members ADAMTS5 and ADAM10." (PMID 26497997, 2015).
breast carcinoma (continued). "Since ADAM17 and ADAM10 are the two best characterized ADAM proteases responsible for HER ligand shedding, we investigated the role of ADAM10 in relation to trastuzumab treatment and resistance in HER2 positive breast cell lines, in vivo and in HER2 positive breast cancer patients." (PMID 24952873, 2014). "Therefore, our results indicate that targeting ADAM10 and ADAM17 might enhance trastuzumab response and overcome acquired trastuzumab resistance in HER2 positive breast cancer patients." (PMID 24952873, 2014). "Since ADAM10 and 17 have been shown to play a role in mediating acquired resistance to trastuzumab through the shedding of HER ligands, it may be important to assess the role of ADAM 10 and 17 proteases as well as other HER ligands in mediating lapatinib resistance in HER2-positive breast cancer." (PMID 25691057, 2015). "AD inhibited ADAM10 protein expression, but not mRNA expression in H1975 and A549 lung cancer cell lines, and BT549 breast cancer cell line in a dosage-dependent manner." (PMID 39211038, 2024). "m62A inhibited ADAM10 protein expression but not mRNA expression in H1975 and A549 lung cancer cell lines, and BT549 breast cancer cell line in a dosage-dependent manner." (PMID 39211038, 2024). "CD inhibited ADAM10 protein expression not mRNA expression in H1975 and A549 lung cancer cell lines, and the BT549 breast cancer cell line, except mRNA expression in BT549 cells, in a dosage-dependent manner." (PMID 39211038, 2024). "Recently, a study done on non-luminal breast cancers (Her2+ and TNBC), published in EBioMedicine, identified soluble APPα that is generated by ADAM10 cleavage of APP, as important in breast cancer tumor migration and proliferation." (PMID 32265938, 2020). "However, the roles of ADAM10 and 17 proteases were not investigated in relation to trastuzumab treatment in HER2-low breast cancer cells." (PMID 38600326, 2024).
glioma (35 papers, 2008 to 2025). A benign or malignant brain and spinal cord tumor that arises from glial cells (astrocytes, oligodendrocytes, ependymal cells). "In addition to ADAM9, several other members of the ADAM family have also been implicated in tumor growth and invasiveness of gliomas, such as ADAM10, ADAM12 and ADAM17." (PMID 27571068, 2016). "We therefore wondered if the membrane-bound actuators responsible for translating NLGN3 exposure into enhanced ADAM10 activity in glioma cells and OPCs were cation-conducting channels sensitive to disruptions in the actin cytoskeleton." (PMID 40791371, 2025). "Taken together, these findings support the idea that that targeting the NLGN3 pathway, including PIEZO1 and ADAM10-mediated cleavage events, represent therapeutic strategies for gliomas." (PMID 40791371, 2025). "ADAM10 is highly expressed in gliomas; however, the mechanism by which ADAM10 balances neuroplasticity and glioma phenotypes through cleaving different substrates remains elusive." (PMID 41018101, 2025). "Remarkably, both ADAM10 G342E (score = −0,81) and ADAM15 N792S (score −1,1) missense pathogenic mutation were associated to low grade glioma, methylated MGMT promoter status and mutant IDH status, which correspond to a positive prognosis in glioma patients." (PMID 38272115, 2024). "While mutations in EFEMP2, ADAM10, SERPINH1, ADAM15, GAS6 and TNXB were detected only in patients with glioma grade 3, mutations in LTBP2, DCN, CRELD1 and HAPLN3 were observed only in patients with glioma grade 4, GBM." (PMID 38272115, 2024). "It has been shown that ADAM10 is overexpressed in high grade gliomas, its inhibition can suppress glioma cell proliferation, migration and invasion." (PMID 38272115, 2024). "Excitingly, ADAM10 inhibitors have been used in clinical trials in the non-glioma setting and appear well tolerated." (PMID 37345193, 2023). "Neuronal activity stimulates NLGN3 extracellular domain shedding into the tumor microenvironment by the protease ADAM10 (A Disintegrin and Metalloprotease 10), thus inducing glioma growth." (PMID 36056393, 2022). "It has been shown that increased levels of soluble L1CAM ectodomain are induced by an upregulation of ADAM10 in glioma, ovarian cancer, and colon cancer." (PMID 34228897, 2022). "In addition, ADAM17 is correlated with a high tumor grade and poor prognosis in patients with glioma and may be a potential diagnostic and therapeutic target, whereas ADAM10 is associated with glioma grade in glioma growth and development, particularly the invasiveness of the glioma." (PMID 34638718, 2021). "Recent studies have shown that ADAM10 is responsible for NLGN3 shedding from glioma cells, so we further studied the role of ADAM10 in this positive feedback loop." (PMID 34485271, 2021). "Inhibition of ADAM10 suppressed the proliferation, migration, and invasion of glioma cells; oppositely, the expression of ADAM10 was correlated with a higher likelihood of lower grade glioma (LGG) in the brain." (PMID 34485271, 2021). "Similar observations have also been seen with glioma stem-like cells, with ADAM10- and ADAM17-dependent shedding of ULBP2." (PMID 33352921, 2020). "ADAM10 is the protease enzyme that cleaves NLGN3 and treatment with small-molecule inhibitors of ADAM10 markedly decreased glioma growth in experimental model systems." (PMID 30279357, 2018). "Transient overexpression of wild-type ADAM10 in human glioma U251N cells stably expressing CAR (U251N CAR) increased shedding of CAR ECD." (PMID 24015300, 2013). "Glioma cell lines from two different species (rat and human) also expressed L1, and proteolysis occurred most likely by ADAM10 to release a large ectodomain." (PMID 19874583, 2009). "Tregs could inhibit tumor growth, and ADAM10 released by glioma cells can induce regulatory B cells, inhibit the activity of CD8 + T cells, and induce Tregs." (PMID 39707577, 2024).
glioma (continued). "We postulated that NLGN3 expressed by older organoids was responsible for this behavior and, indeed, the addition of NLGN3 to young organoids fostered CSC tropism for the organoid, while the administration of an ADAM10 inhibitor prevented the integration of glioma cells into mature organoids." (PMID 37511496, 2023). "In malignant high-grade gliomas, neuronal activity leverages the ADAM10/neuroligin-3 axis to drive tumor growth, which has led to a clinical trial that evaluates an ADAM10 inhibitor (INCB7839) in treating recurrent or progressive pediatric high-grade gliomas (NCT04295759)." (PMID 37891793, 2023). "In addition, studies have shown that glioma cells produce ADAM10 upon activation, and ADAM10 can induce the development of regulatory B cells (Bregs) by converting latency associated peptide (LAP) into TGF-β in B cells." (PMID 36591235, 2022). "The NLGN3/LYN/ADAM10 axis promotes glioma progression via a positive feedback loop." (PMID 34485271, 2021). "GI254023X inhibits metastatic ability but does not inhibit proliferation of glioma cells, suggesting that there may be a corresponding feedback inhibition pathway or other targets except ADAM10 in glioma cells." (PMID 34485271, 2021). "In addition, we found that the expression of ADAM10 in glioma and normal brain tissue was positively correlated with the levels of LYN and NLGN3." (PMID 34485271, 2021). "Additionally, studies on malignant glioma cells revealed that only ULBP2 was shed via ADAM10 and ADAM17 activity." (PMID 33352921, 2020). "Notably, this NLGN3-induced proliferation was attenuated by first pre-treating glioma cells with ADAM10 inhibitor, even in the presence of NLGN3, consistent with the hypothesized role for ADAM10-mediated CSPG4 cleavage in the NLGN3-CSPG4-PIEZO1 mechanism." (PMID 40791371, 2025). "Moreover, ADAM10 was correlated with glioma growth and invasiveness." (PMID 36293469, 2022). "The authors concluded that ADAM10 expression correlates with the grade of malignancy in human glioma and may indicate an important biological role of ADAM10 in glioma growth and development, particularly the invasiveness of gliomas as well as in peritumoral edema formation." (PMID 34638718, 2021). "Moreover, the most recent publications demonstrate that ADAM10 inhibitors might be used in the treatment of glioma patients." (PMID 34638718, 2021). "We observed that glioma cells constitutively shed CSPG4 into their culture medium, a process inhibited by brief treatment with ADAM10 inhibitor GI254023X (5 μM, 15 mins)." (PMID 40791371, 2025). "In glioma, NLGN3 is cleaved from synaptic neurons and OPCs in an activity-dependent fashion by the ADAM10 metalloproteinase." (PMID 38473812, 2024). "A disintegrin and metalloproteinase domain-containing protein 10 (ADAM10) inhibitors have been reported to prevent the release of NLGN3145 and are currently being tested in a Phase 1 clinical trial for high grade gliomas (NCT04295759)." (PMID 38646145, 2024). "As expected, ADAM10 inhibitors, INCB7839 and GI254023X, significantly attenuated the growth of orthotopic xenografts of high-grade glioma." (PMID 38473812, 2024). "Fitting our data, ADAM10 and ADAM17 (over) expression levels likewise significantly correlates with tumor grade in glioma, and both ADAMs are discussed as prognostic markers and therapeutic targets." (PMID 36293469, 2022). "Several studies reported that ADAM9, ADAM10, and ADAM17 showed high expression in glioma; meanwhile, ADAM9, as a potential regulator of glioma invasion, showed higher expression in GBM compared with LGG." (PMID 36172139, 2022). "In summary, in the glioma microenvironment, NLGN3 secreted by neurons and glioma cells activates LYN and upregulates ADAM10 expression, which can cleave NLGN3 to promote its secretion." (PMID 34485271, 2021).
glioma (continued). "Our study demonstrates that glioma-derived NLGN3 promotes glioma progression by upregulating activity of LYN and ADAM10, which in turn promote NLGN3 cleavage to form a positive feedback loop." (PMID 34485271, 2021). "CAR was found to undergo ectodomain shedding by the metalloprotease ADAM10 and regulated intramembrane proteolysis (RIP) in glioma cells." (PMID 31776326, 2019). "We show here a positive correlation between stem/progenitor cells and fibronectin in high grade glioma tissues, as well as an increase in GSC migration through fibronectin during ADAM10 and ADAM17 inhibition, as previously shown with renal cancer cells." (PMID 27541285, 2017). "Intriguingly, ADAM10 levels were significantly correlated with overall survival in low-grade, but not high-grade, gliomas." (PMID 37511496, 2023). "The protease ADAM10 (a disintegrin and Metalloprotease 10) is stimulated by neuronal activity to promote NLGN3 extracellular domain shedding into the tumor microenvironment, which promotes glioma growth." (PMID 36499024, 2022). "Finally, we explored the effect of the ADAM10 inhibitor, GI254023X, on the function of glioma cells." (PMID 34485271, 2021). "Using various approaches, we identified ADAM10 as the metalloprotease mediating constitutive and ionomycin-induced shedding of CAR, as well as shedding induced by high concentrations of PMA, from human glioma cells." (PMID 24015300, 2013).
hepatocellular carcinoma (29 papers, 2014 to 2025). A malignant tumor that arises from hepatocytes. "ADAM10 deficient hepatocellular carcinoma showed less metastasis formation in vivo." (PMID 28260841, 2017). "Along this line, upregulated expression of ADAM17 and/or overexpression of ADAM10 has been associated with tumor progression as well as poor prognosis of numerous human cancers, e.g., gastric, colon, breast, pancreatic and lung cancer and hepatocellular carcinoma." (PMID 36293469, 2022). "And the patients carry ADAM‐10 SNPs rs514049 and rs514049 have a higher chance to develop hepatocellular carcinoma in more advanced TNM stage." (PMID 36946281, 2023). "To that end, we silenced ADAM10 expression using a pool of three siRNAs targeting ADAM10 in Huh-7.5-Fluc hepatoma cells." (PMID 37967063, 2023). "To study a possible impairment of EGFR activation upon ADAM10 inhibition in hepatoma cells, we assessed phosphorylation of ERK1/2 by antibody staining and flow cytometry." (PMID 37967063, 2023). "As EGFR activation is required for productive HCV entry and ADAMs can shed EGF, we asked if ADAM10 also transactivates EGFR in human hepatoma cells." (PMID 37967063, 2023). "In hepatoma cells and primary hepatocytes, ADAM10 and its closest relative ADAM17 (also recognized as tumor necrosis factor α (TNFα) converting enzyme or TACE) show the highest expression levels." (PMID 37967063, 2023). "Expression of ADAM10 was most pronounced in the hepatoma cell line HepG2 and the colon carcinoma cell line HT29." (PMID 36078095, 2022). "Accumulated evidence has demonstrated that ADAM10 participates in the occurrence and development of various tumors, such as hepatocellular carcinoma, hypopharyngeal cancer, esophageal cancer, and PCa." (PMID 35551177, 2022). "In contrast to our results, silencing of ADAM10 alone has been shown to be sufficient to increase apoptosis in hepatocellular carcinoma cells." (PMID 36293469, 2022). "In aother study, ADAM10 decreased E-cadherin protein level and inhibited β-catenin pathway in hepatocellular carcinoma." (PMID 32256208, 2020). "In contrast, siRNA-targeted ADAM10 downregulation was reported to suppress cell proliferation of hepatocellular carcinoma, bladder cancer and nasopharyngeal carcinoma cells." (PMID 30651596, 2019). "The role of ADAM10 in cholangiocarcinoma is the same as that in hepatocellular carcinoma." (PMID 40563539, 2025). "Moreover, the SNPs rs514049 and rs514049 of ADAM‐10 are involved in the hepatocellular carcinoma progression." (PMID 36946281, 2023). "In line with a lack of evidence that EGFR family members are entry factors for CHIKV, VEEV or hCoV-229E, we show that ADAM10 inhibition does not decrease susceptibility to these viruses in hepatoma cells." (PMID 37967063, 2023). "Moreover, siRNA silencing of ADAM10 significantly suppressed cell migration and invasion of hepatocellular carcinoma cells in wound healing and transwell invasion assays in vitro, as well as tumor growth in vivo in a murine xenograph model." (PMID 36293469, 2022). "Moreover, high ADAM10 levels inversely correlated with miR-365 levels were reported as being significantly downregulated in hepatocellular carcinoma cell lines and tumor tissues." (PMID 36293469, 2022). "By contrast, expression levels of p-AKT were significantly decreased in ligamentum flavum cells following ADAM10 silencing, and silencing or ectopic expression of ADAM10 resulted in a marked increase in the phosphorylation of Akt in hepatocellular carcinoma cells." (PMID 36293469, 2022). "Moreover, silencing of ADAM10 reduced cell proliferation in HepG2 hepatocellular carcinoma cells, ligamentum flavum cells, and nasopharyngeal cancer cells." (PMID 36293469, 2022). "For example, miRNA-122 inhibits the tumorigenic properties of hepatocellular carcinoma cells by repressing ADAM10 (a disintegrin and metalloprotease family 10), SRF (serum response factor), and Igf1R (insulin-like growth factor 1 receptor), which promote tumorigenesis." (PMID 28159933, 2017).